MIR4458 (microRNA 4458)
Synonyms: hsa-mir-4458; mir-4458
Gene: MicroRNA gene on chromosome 5 (8,460,925 to 8,460,999, forward strand). Ensembl gene ENSG00000284000.
Homologues: Orthologues: chimpanzee MIR4458 (100% identical).